RAC1 (Rac family small GTPase 1)
Diseases named in the same sentence as RAC1 in open-access papers (continued):
Sharing a sentence is not in itself a finding about the gene and the disease.
diabetic retinopathy (continued). "Experimental models have shown that the inhibitors of its GEFs- Tiam1 and Vav2, inhibit the development of diabetic retinopathy via regulating Rac1-Nox2 signaling." (PMID 34063353, 2021). "In contrast to GEFs, GDIs inhibit Rac1-GEF association to keep it in the cytosolic compartment, and in diabetic retinopathy the binding of Rac1 with GDI is decreased." (PMID 34063353, 2021). "Several inhibitors of Nox2 and Rac1 (and its GEFs) are in experimental or clinical trials for other diseases, and their possible use in diabetic retinopathy will be a welcoming sign for diabetic patients." (PMID 34063353, 2021). "In the pathogenesis of diabetic retinopathy, Rac1 is activated and its expression is upregulated, and activation of Rac1-Nox2-ROS is an early event, which precedes mitochondrial damage-histopathology characteristic of diabetic retinopathy." (PMID 34238980, 2021). "In diabetic retinopathy, inhibition of Rac1 activity protects retinal endothelial cells from hyperglycemia-induced mitochondrial damage and accelerated apoptosis." (PMID 31277234, 2019). "In the pathogenesis of diabetic retinopathy, the Rac1-Nox2 signaling pathway is activated in the retina leading to oxidative stress, suggesting that Rac1 must be post-translationally modified to be more hydrophobic." (PMID 31277234, 2019). "In the pathogenesis of diabetic retinopathy, gene transcripts of Rac1 are increased in the retina and its vasculature." (PMID 31277234, 2019). "This review focusses on the role of Rac1 and its regulation in the development and progression of diabetic retinopathy, and discusses some possible avenues for therapeutic interventions." (PMID 31277234, 2019). "The present review focuses on Rac1-Nox2, and the role of other isoforms of Nox in diabetic retinopathy is beyond the scope of this review." (PMID 31277234, 2019). "Rac1 plays a critical role in the pathophysiology of diabetic retinopathy by activating Nox2, which leads to excessive free radical generation." (PMID 31277234, 2019). "Administration of inhibitors of Tiam1 and Vav2, inhibit Rac1-Nox2 signaling in diabetic animal models, and prevent the development of diabetic retinopathy." (PMID 31277234, 2019). "In conclusion, as detailed above, in the pathogenesis of diabetic retinopathy once mtDNA is damaged, due to dysfunctional electron transport chain, the vicious cycle of ROS continues to self-propagate, but activation of Rac1-Nox2 precedes mitochondrial damage." (PMID 31277234, 2019). "Diabetic retinopathy is a progressive disease, and activation of Rac1-Nox2 is one of the early events in its pathogenesis." (PMID 30347077, 2018). "Rac1, via Nox2, elevates cytosolic ROS levels, and ROS damage mitochondria and increase capillary cell apoptosis, which, ultimately, results in diabetic retinopathy." (PMID 30347077, 2018). "Experimental models have shown that the activation of Rac1-Nox2-ROS precedes mitochondrial damage, and the development of diabetic retinopathy." (PMID 30347077, 2018). "Our previous work has shown that the presence of hyperlipidemia in a hyperglycemic milieu (type 2 diabetic model) further exacerbates the activation of Rac1–Nox2–ROS signaling, and accelerates the development of diabetic retinopathy by accelerating and exacerbating mitochondrial damage-apoptosis." (PMID 36202842, 2022). "In the pathogenesis of diabetic retinopathy, activation of Rac1 is an early event, and sustained activation of Rac1-Nox2-ROS damages the mitochondria, initiating a self-propagating a vicious cycle of free radicals, making it an attractive target for therapeutic intervention." (PMID 34063353, 2021). "Thus, there remains a strong possibility of similar epigenetic modifications of Rac1 promoter in the retinal microvasculature from human donors with diabetic retinopathy, which would further strengthen the clinical significance of the results presented here." (PMID 34238980, 2021).
diabetic retinopathy (continued). "Thus, inhibition of Rac1 activation, an early event in the pathogenesis of diabetic retinopathy, will halt the vicious cycle of ROS accumulation, and ameliorate further progression of the disease." (PMID 31277234, 2019). "Rac1 activation was also demonstrated in a diabetic retinopathy model." (PMID 27527066, 2016). "Experimental models have revealed that generation of cytosolic ROS via Rac1-Nox2 signaling and the activation of MMP-9 are early events in the pathogenesis of diabetic retinopathy." (PMID 36672234, 2023). "Cross-talk between ceramides and Rac1 signaling via regulatory factors, including Tiam1 and Vav2, in the development of diabetic retinopathy, however, cannot be ruled out." (PMID 36202842, 2022). "High-glucose-induced Rac1-palmitoylation has been suggested to be a driving force behind the activation of NOX, which in turn would alter the localization of Rac1 remodeling in diabetic retinopathy." (PMID 34360006, 2021). "Thus, using both in vitro and in vivo models of diabetic retinopathy, our results provide strong evidence of relationship between H3K9 methylation and DNA modifications of Rac1 promoter in its transcriptional activation." (PMID 34238980, 2021). "In the later stages of diabetic retinopathy, via regulating angiogenic signaling pathways of VEGF and hypoxia-inducible factors, Rac1 could contribute to the neovascularization." (PMID 34238980, 2021).
heart failure (13 papers, 2014 to 2025). Inability of the heart to pump blood at an adequate rate to meet tissue metabolic requirements. "Transgenic overexpression of zDHHC3 in cardiomyocytes results in severe heart failure, which is associated with increased Rac1 S-palmitoylation and GTP loading." (PMID 40924486, 2025). "Cardiomyocyte-specific overexpression of RhoA or Rac1 causes cardiac failure in mice, and RhoGTPase signaling is activated in murine cardiomyopathy and human heart failure." (PMID 37926281, 2023). "In a patient with heart failure, Nox mediated ROS generation raised in the left ventricular myocardium and associated with the rise in Rac1 GTPase activity, whereas statin therapy was able to reduce Rac1 activity in the heart." (PMID 27774507, 2016). "The results have shown some genomic mechanisms contributing to myocardial infarction, whether it be the enrichment of the RAC1 protein leading to the regulation of NADPH oxidase causing heart failure, or the altered regulation in the PP2A gene leading to heart failure and arrhythmia." (PMID 34805976, 2021). "Therapeutic approaches to inhibit Rac1 signaling in cardiomyocytes have been proposed as potential treatments for heart failure." (PMID 41333012, 2025). "In this study, we elucidated what we believe is a novel role for S-palmitoylation of Rac1 in the regulation of its cardiomyocyte signaling activity, β-adrenergic responsiveness, and propensity to heart failure in response to pathologic cardiac stress." (PMID 40924486, 2025). "High levels of RGS3L, as found in heart failure, redirect the Gi-mediated Rac1 activation into a Gi-mediated RhoA/ROCK activation." (PMID 35230541, 2022). "Numerous studies have confirmed that Rac1 is involved in pressure overload-induced heart failure and the MEK-ERK1/2 signaling pathway." (PMID 34692792, 2021). "Indeed, zDHHC3 transgenic mice develop cardiomyopathy and heart failure with enhanced Rac1 S-palmitoylation and plasma membrane localization, along with activation of other Rho GTPase family members." (PMID 37926281, 2023). "Indeed, the efficacy of statin drugs in heart failure treatment is thought to be mediated in part through repression of Rac1 via inhibition of prenylation and antagonism of maladaptive Rac1 signaling and oxidative stress." (PMID 37926281, 2023). "Interestingly, statin drugs commonly prescribed to treat cardiovascular disease repress membrane localization, activation, and abundance of Rac1 in cardiomyocytes and similarly reduce cardiac Rac1 activity and oxidative stress in human heart failure." (PMID 37926281, 2023). "In patients with heart failure, statin treatment reduces Rac1 function, NADPH oxidase activity and levels of reactive oxygen species, a finding consistent with our observation that simvastatin pretreatment reduces IL-1β/bradykinin mediated microvascular hyperpermeability." (PMID 33327440, 2020). "We investigated the relationship of Rac1, atrial endothelial thromboprotective markers and AF inducibility and if simvastatin has a potential beneficial effect on a myocardial infarction (MI)-induced heart failure (HF) rat model." (PMID 25153633, 2014). "Thus, identifying cardiomyocyte-specific mechanisms that either regulate or are regulated by Rac1 signaling could aid in the identification of novel targets for therapeutic development in heart failure." (PMID 41333012, 2025). "Taken together, our data demonstrate an interesting new mechanism involving an M2R-induced switch which regulates the Rac1–RhoA balance in cardiomyocytes, and could account for the M2R-induced increased cardiac contractility seen in experimental heart failure and neonatal rat hearts." (PMID 35230541, 2022). "Thus, the unmasked upstream signaling pathway consisting of PGE2, EP3, Rac1, and PKD may provide a number of new drug target candidates for the treatment of heart failure in the specific setting of inflammatory causes." (PMID 29907596, 2018).
heart failure (continued). "Our results demonstrate an adaptive role for S-palmitoylation–dependent regulation of localized Rac1 activity in cardiomyocytes in vivo, which is essential for proper cardiac resilience against persistent PKA activation and heart failure in response to chronic hypertrophic stimulation." (PMID 40924486, 2025). "The unmasked upstream signaling pathway consisting of PGE2, EP3, Rac1, and PKD may provide a number of new drug target candidates for the treatment of heart failure, in particular of inflammatory cardiomyopathies." (PMID 29907596, 2018). "As this muscarinic inotropic mechanism bona fide bypasses cAMP signaling it might be part of the beneficial effects of non-neuronal ACh in heart failure together with the afore discussed decrease in Rac1-dependent ROS production and cardiomyocyte hypertrophy." (PMID 35230541, 2022).
Macrocephaly (13 papers, 2019 to 2025). Occipitofrontal (head) circumference greater than 97th centile compared to appropriate, age matched, sex-matched normal standards. "This important number of independent individuals with a similar phenotype reduces the potential contribution of other variants to the phenotype and strongly suggests that hyperactivation of RAC1 by TRIO is associated with macrocephaly." (PMID 32109419, 2020). "Nonetheless, our data provide strong evidence that missense TRIO mutations inducing RAC1 overactivation are associated with macrocephaly." (PMID 32109419, 2020). "PAK1 is a common interactor to RAC1 and RAC3, and is associated with an autosomal dominant NDD known as intellectual developmental disorder with macrocephaly, seizures, and speech delay (IDDMSSD, OMIM # 618158)." (PMID 34943902, 2021).
schizophrenia (13 papers, 2015 to 2024). A major psychotic disorder characterized by abnormalities in the perception or expression of reality. "p250GAP, also called RICS or Grit, shows GAP activity toward inhibition of RhoA, Rac1, and Cdc42. p250GAP gene was recently found as a candidate gene for susceptibility to schizophrenia, suggesting its potential importance in brain development and function." (PMID 25879033, 2015). "Furthermore, RAC1 overactivation resulting from Disrupted-in-Schizophrenia 1 (DISC1) downregulation is a major contributing factor in the loss of neuronal spines in schizophrenia patients." (PMID 38674040, 2024). "RAC1 contributes to the pathogenic mechanism of schizophrenia as the downstream signaling central molecule of several schizophrenia risk genes, including disrupted-in-schizophrenia 1 (DISC1) and brain-derived neurotrophic factor (BDNF), which regulate neuroplasticity and neural connectivity." (PMID 36680208, 2023). "Disrupted-in-Schizophrenia-1 (DISC1), a candidate responsible gene for pathogenesis underlying schizophrenia, plays a role in the post-synaptic density associated with Rac1 The transient and short-term depletion of DISC1 activates Rac1 and induces spine growth in primary cultured neurons." (PMID 36301793, 2022). "Notably, RAC1 acts as a regulator of OL differentiation and myelination, suggesting that RAC1 dysregulation may not only affect synapse maintenance but also contribute to white matter loss in schizophrenia." (PMID 38674040, 2024). "Here, we further discovered that ERVWE1 led to great variability in RAC1 levels, indicating a role of ERVWE1 in the pathogenesis of schizophrenia via RAC1." (PMID 36680208, 2023). "Recent studies have suggested that Arp2 and RAC1 are significantly lower in schizophrenia, similar to our findings." (PMID 36680208, 2023). "Postmortem studies indicate that RAC1 is significantly decreased in the gray matter of subjects with schizophrenia." (PMID 36680208, 2023). "Complex and multifaceted mechanisms converging on Rac1 dysfunction are implicated in the pathogenesis of additional conditions with a primary neurological involvement, including ASD, Rett syndrome, and schizophrenia." (PMID 34943902, 2021). "Among others, a direct link between the underlying pathogenic mechanisms and Rac1 has been suggested in autism spectrum disorders (ASD), schizophrenia, Fragile X syndrome, Rett syndrome, and Huntington’s disease." (PMID 34943902, 2021). "RAC1 can be also involved in the pathogenesis of schizophrenia as the downstream signaling hub molecule for the proteins encoded by risk genes such as DISC1, KALRN, and TIAM1." (PMID 34943902, 2021). "The dysregulation of Rac1 has been indicated in the processes of neuronal morphogenesis, migration, and synaptic plasticity in neurodevelopmental disorders such as schizophrenia, ASD, and FXS, as highlighted in the review." (PMID 33299404, 2020). "Kalirin 7 (Kal-7) is a Rac1 GEF that was found to be transcriptionally downregulated in the prefrontal cortices of patients with schizophrenia." (PMID 33299404, 2020). "The localization of Kalirin-7 and the duration of Rac1 activation are regulated by the schizophrenia-related factor DISC1 (disrupted-in-schizophrenia 1)." (PMID 25879033, 2015). "Abnormal RAC1 is responsible for delayed neuronal death, neuronal degeneration, and cognitive dysfunction in hippocampal neurons and contributes to different neurodevelopmental disorders, such as schizophrenia." (PMID 36680208, 2023). "Arp2, one of the genes downstream of the RAC1/WAVE1 signaling pathway, is significantly lower in dorsal lateral prefrontal cortex (DLPFC) layer 3 and 5 pyramidal cells in schizophrenia." (PMID 36680208, 2023). "We observed that the levels of serum RAC1 and WAVE1 were substantially lower in schizophrenia patients than those in healthy individuals." (PMID 36680208, 2023).
schizophrenia (continued). "Our study showed that ERVWE1 inhibited the activity of RAC1 and WAVE1 through Wnt5a in neurons, suggesting that ERVWE1 triggered schizophrenia by regulating RAC1 and WAVE1 in schizophrenia." (PMID 36680208, 2023). "The Rac1 protein is activated by the N-methyl-d-aspartate receptor (NMDAR) and is important for disrupted in schizophrenia 1 (DISC1) function in the maintenance of spine morphology and function." (PMID 29695761, 2018). "The research has found that in the astrocytes of schizophrenia, the levels of PYGM and RAC1 (a kinase that regulates the activity of PYGM) involved in astrocytes metabolism are reduced, leading to a transient partial energy deficiency in the dorsolateral prefrontal cortex." (PMID 35990602, 2022).
Cerebral ischemia (12 papers, 2010 to 2024). Restriction of arterial blood supply to the brain associated with insufficient oxygenation to support the metabolic requirements of the tissue. "Cerebral ischemia induces tight junction (TJ) protein degradation via mechanisms involving activation of the B1R/ROCK/Rac1 pathway." (PMID 38872149, 2024). "Further, axon repair and nerve regeneration were promoted after cerebral ischemia through Netrin-1/Rac1/Cdc42 signalling pathways." (PMID 36975497, 2023). "Several studies have shown that Rac1 protects the brain‐blood barrier and exerts a regenerative effect on axons after cerebral ischemia." (PMID 33533575, 2021). "The ubiquitin E3 ligase TRAF6 promotes cerebral ischemia-reperfusion injury through increased ubiquitination and activation of Rac1." (PMID 33609088, 2021). "Intriguingly, it has been reported that interaction of mitochondrial Rac1 with Bcl-2 is implicated in generation of ROS, in which inhibition of formation of Rac1/Bcl-2 ameliorates neuronal oxidative stress damage following cerebral ischemia reperfusion." (PMID 34658788, 2021). "By reviewing the literature, we also found that RPL17, Tuba, and Rac1 have a great relationship with the pathogenesis of cerebral ischemia and were each in one of the three more important pathways enriched by 21 DEPs." (PMID 31223330, 2019). "This validated the identification of the 21 DEPs and confirmed a role RPL17, Tuba, and Rac1 involved in three important pathways in cerebral ischemia." (PMID 31223330, 2019). "To explore how the loss of CK2 activity induced by I/R promotes the activation of NADPH oxidase via translocation of Rac1 and p47phox in cerebral ischemia, we examined the possibly physical interactions between CK2α and p47phox or between CK2α and Rac1." (PMID 27276705, 2016). "Taken altogether, our findings suggest NSC23766 to be an effective Rac1 inhibitor, having the ability to counteract Rac1 activation at 3 h following cerebral ischemia." (PMID 20830300, 2010). "The current study adds to growing evidence of an important role of Rac1 GTPase in oxidative stress and neuronal cell death following cerebral ischemia." (PMID 20830300, 2010). "In consistent with the in vitro findings, after I/R injury, 2-APB promoted Nur77 translocation from nucleus to mitochondrial, where it correlated with Rac1, initiated mitophagy, cleared off dysfunctional mitochondrial, thereby protected against cerebral ischemia." (PMID 34551394, 2021). "In conclusion, our data indicate that a dose and stage dependent treatment with histidine promotes astrocyte migration towards the infarct area through H2 receptor and subsequent up-regulation of active Rac1, which benefits long-term neurological function recovery after cerebral ischemia." (PMID 26481857, 2015). "Thus, it is postulated that regulation of Tiam1 and Trio following cerebral ischemia contributes to the enhanced Rac1 GTPase activation following ischemia/reperfusion." (PMID 20830300, 2010). "Our study also provides insight into how Rac1 GTPase activation contributes to cerebral ischemia pathology, by demonstrating that Rac1 GTPase activation is critical for induction of oxidative stress in the hippocampal CA1 region following ischemia/reperfusion injury." (PMID 20830300, 2010). "For instance, previous work by our group has shown that Rac1 GTPase also has an important role in activation of the proapoptotic JNK signaling pathway following cerebral ischemia, as Rac1 binds to a scaffold complex of POSH and MLK3 and facilitates activation of JNK." (PMID 20830300, 2010). "Hence, the NM II-dependent release of GEFs may contribute to the pathogenesis of cerebral ischemia by the Rac1-dependent generation of reactive oxygen species and postischemic morphological changes." (PMID 24752242, 2014).